ADAM10 (ADAM metallopeptidase domain 10)
Diseases named in the same sentence as ADAM10 in open-access papers (continued):
Sharing a sentence is not in itself a finding about the gene and the disease.
Sepsis (continued). "Thus, ADAM10 might be clinically important and play a critical role in the pathogenesis of the development of sepsis, with potentially important therapeutic implications." (PMID 25888255, 2015). "However, although several studies have suggested a correlation between ADAM10 and sepsis, to date, no study has examined the association between ADAM10 polymorphisms and sepsis." (PMID 25888255, 2015). "Our study has shown that plasma VE-Cadherin levels can be a valuable biomarker for predicting sepsis in LVAD patients, with predictive performance further enhanced when combined with circulating ADAM10 levels." (PMID 41596215, 2026). "Plasma VE-Cadherin levels can be a valuable biomarker for predicting sepsis in LVAD patients, with predictive performance further enhanced when combined with circulating ADAM10 levels." (PMID 41596215, 2026). "Although WT control mice (VE-Cad ADAM10+/+) succumbed to sepsis induced by i.v. inoculation of 1 × 108 CFU S. aureus USA300/LAC, endothelial ADAM10-knockout mice (VE-Cad ADAM10–/–) were protected against lethal infection." (PMID 37788087, 2023). "Moreover, our findings suggest that further investigation of cytotoxin activity across a broader array of leading sepsis pathogens from the Enterobacteriaceae, Clostridiaceae, and Streptococcaceae families may expand our understanding of ADAM10 dependence in pathogenesis." (PMID 37788087, 2023). "However, the specific role of miR-23b in the regulation of ADAM10 and sepsis remains unclear." (PMID 31780861, 2019). "miR-23b expression was downregulated in the peripheral blood mononuclear cells of sepsis patients and LPS-induced THP-1 cells and was negatively correlated with the expression of ADAM10 and inflammatory cytokines." (PMID 31780861, 2019). "In the present study, decreased expression of miR-23b was observed in the PBMCs of sepsis patients and LPS-induced THP-1 cells, which was negatively correlated with the expression of ADAM10 and inflammatory cytokines." (PMID 31780861, 2019). "Sepsis induced the expression of three members of the disintegrin and metalloproteinase (ADAM) family, ADAM17, ADAM19 and ADAM10, and compstatin treatment mitigated the enhancement of these genes." (PMID 26337158, 2015). "Thirdly, because circulating VE-Cadherin and ADAM10 were not measured at the time of sepsis onset, we were unable to evaluate how these biomarkers change during active sepsis." (PMID 41596215, 2026). "Baseline elevated plasma ADAM10 and VE-Cadherin levels were observed in the sepsis group patients when compared to the no-sepsis group patients." (PMID 41596215, 2026). "The differences in the expression levels of ADAM10 substrates (CX3CL1, IL-6R and TNF-a) and the pro-inflammatory cytokines IL-1ß and IL-6 according to the ADAM10 genotype were analyzed in PBMCs from the sepsis patients and the controls." (PMID 25888255, 2015). "Moreover, after LVAD implantation, patients in the sepsis group had significantly higher plasma levels of ADAM10 and VE-Cadherin than those without sepsis." (PMID 41596215, 2026). "While we did not observe differences in sepsis outcomes in VE-Cad ADAM10–/– mice following infection with GBS or C. albicans, subtle differences may exist that exceed the sensitivity of detection in a mouse model system." (PMID 37788087, 2023). "Consistently, our previous study showed that the ADAM10 mRNA expression levels in the sepsis group were significantly higher than in controls, underscoring the fact that EGR1 correlates well with ADAM10 expression in sepsis patients and potentially plays a crucial role in the progression of sepsis." (PMID 31387910, 2019). "Furthermore, we observed that circulating ADAM10 levels increased dramatically within the first 2 weeks, then returned to near baseline levels in the no-sepsis group, whereas they remained elevated in the sepsis group." (PMID 41596215, 2026).
Sepsis (continued). "Because the inflammatory system is vast and complex, the increase in the ADAM10 mRNA level attributable to the rs653765 CC genotype may not be sufficiently strong to significantly influence inflammatory signaling during the development of severe sepsis." (PMID 25888255, 2015). "Furthermore, we found that the ADAM10 expression level in the sepsis subgroups was consistent with the results of our case-control study and that the healthy controls did not display altered ADAM10 expression or the differential expression of ADAM10 between the different genotypes." (PMID 25888255, 2015).
dementia (13 papers, 2009 to 2023). Loss of intellectual abilities interfering with an individual's social and occupational functions. "YWHAZ, a member of the 14‐3‐3 protein family, is involved in the regulation of brain neural development and signal transduction, while ADAM10 is associated with Aβ, the hallmark pathology of AD, which are also considered to have great application value in the clinical diagnosis of dementia." (PMID 36254251, 2022). "Radiation is an important risk factor for age-related diseases such as CAA and dementia, and the radiation-stimulated downregulation of ADAM10 identified here in senescent cells suggests ADAM10 may be a key player in the molecular etiology of radiation risks for CAA, dementia and potentially AD." (PMID 28437250, 2017). "More studies need to be performed using a larger number of participants and investigating the levels of plasma ADAM10 in different dementias in order to confirm the specificity of this marker." (PMID 33670873, 2021). "HT can improve dementia through regulating ADAM10 expression." (PMID 29843688, 2018). "Therefore, considering the pathological connection with Aβ deposition and the significant correlation with the clinical symptoms of dementia, ADAM10 and BACE1 could serve as peripheral platelet biomarkers for early diagnosis of AD." (PMID 33942972, 2021). "Among them, platelet tau, A-β-PP (especially coated platelets) and secreted ADAM-10 and BACE1 are the most promising for clinical diagnosis of dementia." (PMID 33824766, 2021). "AD cases over the age of 80 years could have been more representative of the age-related downregulation of ADAM10 (even in the absence of rare genetic variants), though patients in this older age range do not undergo lumbar tap for AD core biomarkers as often as patients with younger onset dementia." (PMID 37047093, 2023).
ovarian carcinoma (13 papers, 2016 to 2025). A malignant neoplasm originating from the surface ovarian epithelium. "Furthermore, we wanted to know whether, in ovarian cancer cells, the transition of these forms is controlled by proteases, i.e. ADAM10 or ADAM17, which had been associated with CX3CL1 cleavage in other cell systems before." (PMID 39862711, 2025). "The premature version of miR-363-3p, miR-363, correlated with overall survival (OS), while ADAM10 corresponded with progression-free survival (PFS) in ovarian cancer patients." (PMID 37781085, 2023). "The Kaplan-Meier Plotter subset Ovarian cancer mRNA showed that upregulated ADAM10 expression correlated with poorer PFS in 1436 ovarian cancer patients." (PMID 37781085, 2023). "ADAM10 has been shown to be present and active in exosome like extracellular vesicles (EVs) (e.g., derived from Hodgkin lymphoma and ovarian carcinoma cells)." (PMID 35163191, 2022). "In this regard it is of interest that functionally active ADAM10 has been found in exosomes from ovarian carcinoma cells where it contributes to L1 and CD44 cleavage and in exosomes of primed B-cells." (PMID 28367112, 2017). "The effect of ADAM10 on ovarian cancer prognosis supported the role of ADAM10 in ovarian cancer." (PMID 36922678, 2023). "Indeed, inhibition of ADAM10/17-mediated CXCL16 shedding reduced the migrating potential of ovarian cancer cells." (PMID 27471636, 2016). "Preventing the production of sBCAM by blocking ADAM10 and/or other relevant metalloproteinases may also represent an option, but is less likely to succeed in view of the failure of marimastat in clinical trials, including ovarian cancer." (PMID 36647260, 2023). "This combinatory effect of ADAM17 or ADAM10 inhibition and cisplatin treatment has not been shown before in ovarian cancer, to the best of our knowledge." (PMID 29662625, 2018).
diabetes (12 papers, 2010 to 2026). "Secondly, we investigated if changes in serum levels of ADAM10 in diabetes were associated with changes in its substrates." (PMID 35705192, 2022). "Several other kinases are known to be activated in diabetes and it is possible that GSK3β is only one of the mechanisms that triggers ADAM10 and 17 upregulation." (PMID 37762417, 2023). "The current study demonstrated for the first time that ADAM10/CXCL16/NF-κB mediated STZ-induced diabetes." (PMID 35335970, 2022). "Serum ADAM10 levels were significantly higher in individuals with diabetes than in the control and remained significant even after adjusting for body mass index (BMI) (P < .01)." (PMID 35705192, 2022). "Serum ADAM10 was increased in subjects with diabetes compared with control (40.5 ng/mL [22.3‐65.7] vs 10.3 ng/mL [7.0‐17.9], respectively; P < .01); the highest levels were seen in insulin‐treated subjects." (PMID 35705192, 2022). "Subjects with diabetes had higher serum sLOX‐1 than the control (110 pg/mL [89‐153] vs 104 pg/mL [85‐138], respectively; P < .01), and there was a significant correlation between serum ADAM10 and sLOX‐1 (r = 0.26, P < .01)." (PMID 35705192, 2022). "This may potentially affect the specificity of systemic ADAM10 level as a biomarker when diabetes is present as a comorbid condition." (PMID 35705192, 2022). "In diabetes, it has been suggested that urinary ADAM10 might be a biomarker of early diabetic nephropathy." (PMID 35705192, 2022). "The increase in serum ADAM10 levels in diabetes was accompanied by changes in serum sLOX‐1." (PMID 35705192, 2022). "A recent study has reported that tissue expression of ADAM10 is increased in diabetes." (PMID 35705192, 2022). "We conclude that ADAM10 may contribute, at least in part, to the exaggerated neointimal formation observed in diabetes." (PMID 24386293, 2013). "Indeed, the role of ADAM10 in diabetes is still questionable." (PMID 35335970, 2022). "Hence, the ubiquitous nature of ADAM10 expression and the upregulation in disease states may affect its use as a biomarker in situations with co‐existing comorbidities like diabetes." (PMID 35705192, 2022). "Our data therefore suggest that ADAM10 might be involved in the regulation of RAGE in diabetes." (PMID 26325204, 2015). "Thus activation of ADAM10-mediated cleavage of RAGE and APP should counteract the development of AD, and furthermore stimulation of RAGE shedding should prevent at least some pro-inflammatory effects associated with diabetes mellitus." (PMID 22860017, 2012). "While the exact mechanism by which ADAM-10 is increased in the retinas of diabetics remains to be determined, these results indicate that ADAM-10 may contribute to the cleavage of membrane bound betacellulin that causes increased retinal vascular permeability seen as a complication of the disease." (PMID 20976146, 2010). "Many previous studies have proven that ADAM10 and ADAM17 also play an important role in the development and progression of metabolic syndrome, and thus the development of inflammation, obesity and many diseases, including diabetes mellitus type 2 (DMT2)." (PMID 36286024, 2022). "The precise in vivo and particularly cell‐specific and tissue‐specific effects of ADAM10 in diabetes still largely need to be determined, and our study is not powered to evaluate the role of ADAM10 as a marker of diabetic vascular complications." (PMID 35705192, 2022). "We showed that mRNA of TMPRSS2 and ADAM10, ADAM17 and Furin as well as MAS were all up-regulated in the diabetic heart and may increase receptor internalization and shedding in diabetes." (PMID 33906662, 2021). "This study has identified significantly increased expression of ADAM10 in the ISR versus non-ISR segment in diabetic minipigs and implicates ADAM10 in the enhanced neointimal formation observed in diabetes after vascular injury." (PMID 24386293, 2013).
diabetes (continued). "Although ADAM10 appears to contribute to SMC properties in the non-diabetic state, it is further elevated in diabetic conditions via at least RAGE pathway, which suggests that ADAM10 mechanism may contribute to the enhanced neointimal formation that occurs in diabetes." (PMID 24386293, 2013).
prion disease (12 papers, 2011 to 2024). A transmissible disease that is caused by a protein that is able to induce abnormal folding of normal cellular proteins, leading to characteristic spongiform brain changes, which are associated with neuronal loss without an inflammatory response. "The only other study investigating the role of ADAM10 in prion disease showed that transgenic overexpression of bovine ADAM10 in mice led to prolongation of prion disease, a finding which is complementary to our data on the effect of ADAM10 deficiency." (PMID 25654651, 2015). "In the present study, we analysed the expression of TREM2 and its main sheddase ADAM10 in the brain of sporadic Creutzfeldt-Jakob disease (sCJD) patients and evaluated the role of CSF and plasma sTREM2 as a potential diagnostic marker of prion disease." (PMID 33881612, 2021). "However, due to the perinatal lethality of these mice we were unable to investigate the impact of ADAM10 deficiency on the course of prion disease." (PMID 25654651, 2015). "Notably, a recent study investigating the role of the extracellular matrix component heparan sulfate as a cofactor in prion diseases revealed that prion deposits in brains of transgenic mice infected with CWD prions largely consisted of heparan sulfate-associated ADAM10-cleaved PrPSc." (PMID 35084572, 2023). "Fittingly, in prion disease mouse models, ADAM10 expression correlates with incubation and survival time; and sPrP levels inversely correlate with PrPSc formation." (PMID 38980441, 2024). "ADAM10 also plays a dual role in prion disease since, on the one hand, ADAM10 inhibits the transition of cellular prion protein (PrPc) to pathological prion protein (PrPsc), but on the other hand, promotes the spread of PrPsc." (PMID 37175729, 2023). "The cellular prion protein (PrPc) as a glycosylphosphatidylinositol (GPI)-anchored protein is shed at the plasma membrane by ADAM10, while a pathological and misfolded form of the prion protein (PrPsc) is formed in prion disease." (PMID 33413403, 2021). "We have previously shown that the metalloprotease ADAM10 is the responsible protease for the shedding of PrPCin vivo and that impaired shedding has significant consequences for prion diseases." (PMID 30608982, 2019). "Shedding of almost full-length PrPC into the extracellular space by the metalloprotease ADAM10 is of peculiar relevance since soluble PrP stimulates axonal outgrowth and is protective in neurodegenerative conditions such as Alzheimer’s and prion disease." (PMID 29625583, 2018). "Owing to the importance of its substrates, ADAM10 is a potential therapeutic target for cancer, neurodegenerative diseases such as Alzheimer's and prion diseases, bacterial infection and inflammatory diseases such as heart attack, stroke and asthma." (PMID 28620033, 2017). "PrPC is shed at the plasma membrane by the metalloprotease ADAM10, yet the impact of this on prion disease remains enigmatic." (PMID 25654651, 2015). "Our data support a dual role for ADAM10-mediated shedding and highlight the role of proteolytic processing in prion disease." (PMID 25654651, 2015). "It is virtually impossible to dissect out the individual contribution of the multitude of ADAM10 targets to the pathophysiology of prion disease." (PMID 25654651, 2015). "Another microglia-related mechanism relevant to prion disease and influenced by ADAM10 is the Cx3cl1/Cx3cr1 signaling complex." (PMID 25654651, 2015). "In contrast, spread of prion pathology within the brain is reduced, thus indicating a dual role for ADAM10 in the pathophysiology of prion disease." (PMID 25654651, 2015). "Another important topic is the role of PrP sheddase ADAM10 in prion diseases." (PMID 37854584, 2023). "Focusing on neurodegeneration, we have recently shown a significant impact on the course of prion disease in mice by conditional depletion of the sheddase ADAM10, as have others by overexpression of exogenous ADAM10 or by transgenic expression of anchorless versions of PrP." (PMID 29625583, 2018).